PIN1 (peptidylprolyl cis/trans isomerase, NIMA-interacting 1)
Diseases named in the same sentence as PIN1 in open-access papers (continued):
Sharing a sentence is not in itself a finding about the gene and the disease.
B cell lymphoma (3 papers, 2013 to 2019). "Pin1 was shown to associate with c-Rel and influence c-Rel nuclear translocation in human B cell lymphoma cell lines as pharmacologic inhibition or knockdown of Pin1 decreased c-Rel nuclear translocation." (PMID 31277480, 2019). "It becomes apparent that PML is regulated by different molecules in different cancer types, e.g., by E6AP in B-cell lymphoma, CK2, and PIAS1 in NSCL cancer whereas KLHL20/Pin1 in prostate adenocarcinoma." (PMID 23730625, 2013).
epilepsy (3 papers, 2022 to 2024). A brain disorder characterized by episodes of abnormally increased neuronal discharge resulting in transient episodes of sensory or motor neurological dysfunction, or psychic dysfunction. "Electrophysiological studies of ion channels have also revealed some of the pathophysiological mechanisms underlying Pin1 and epilepsy." (PMID 36304997, 2022). "The evidence discussed in this review supports the idea that Pin1 is implicated in the onset and progression of epilepsy." (PMID 36304997, 2022). "In line with this hypothesis, Pin1 has been reported to take part in neuro-associated diseases, including epilepsy." (PMID 36304997, 2022). "The function of Pin1 in epilepsy may be associated with some classical signaling pathways, such as the Notch1 signaling and PI3K/Akt signaling pathways." (PMID 36304997, 2022). "The mechanism by which Pin1 regulates epileptic ion channels may illuminate the underlying roles of Pin1 in epilepsy." (PMID 36304997, 2022). "In addition, Pin1 is closely linked to the onset and progression of epilepsy." (PMID 38891776, 2024). "Therefore, it is reasonable to hypothesize that Pin1 is associated with the development of epilepsy." (PMID 36304997, 2022). "In epilepsy, early studies on the role of Pin1, as recently reviewed by Chen and colleagues, suggest that Pin1 regulates the stabilities of several disease-related proteins." (PMID 38727267, 2024). "The phosphorylation would reduce conformational heterogeneity and flexibility of the phospho-binding loop upon S16 phosphorylation and abrogates the binding capacity of Pin1 afterward, which would definitely affect the neuronal signaling in epilepsy." (PMID 36304997, 2022). "Given the critical role of Pin1 in neurological diseases, we discuss in this review the recent findings of the dysregulation, mechanisms, and biological functions of Pin1 in epilepsy." (PMID 36304997, 2022). "More research in animal models and technological innovation would be helpful to further boost the success of Pin1 in epilepsy treatment." (PMID 36304997, 2022). "Thus, the interaction between PKC and Pin1 and its function and molecular mechanism in the development of epilepsy is urgently needed." (PMID 36304997, 2022). "Additionally, a pilocarpine-induced epileptic mouse model has also been used to verify the expression of Pin1 in epilepsy, and the results are consistent with those in humans, which supports the antiepileptic effect of Pin1." (PMID 36304997, 2022). "However, more evidence is needed to clarify the potential role of Pin1 in neuronal signaling, particularly in the occurrence of epilepsy." (PMID 36304997, 2022). "The effect of Pin1 on the progression of epilepsy in animal models is discussed as well." (PMID 36304997, 2022). "Pin1 plays a critical role in preventing pathologies in epilepsy by regulating synapses; thus, it is reasonable to speculate that the upregulation and/or activation of Pin1 may be helpful for epilepsy treatment." (PMID 36304997, 2022). "In addition, we highlight the significance and potential applications of Pin1 in neuronal diseases, especially epilepsy." (PMID 36304997, 2022). "Pin1 has strong neuroprotective effects in the progression of epilepsy, and the Pin1/NMDAR complex, Pin1-CaMKII-AMPA receptor axis and Pin1-NL2/gephyrin- GABAergic signaling may all be involved in the mechanism." (PMID 36304997, 2022). "The expression of Pin1 is dramatically decreased in the neocortex of epilepsy patients." (PMID 36304997, 2022). "This information will lead to a better understanding of Pin1 signaling pathways in epilepsy and may facilitate development of new therapeutic strategies." (PMID 36304997, 2022). "Because of the close relationship between the AMPA receptor and Pin1, this novel therapy may broaden the spectrum of Pin1 in the treatment of epilepsy." (PMID 36304997, 2022).
epilepsy (continued). "Spontaneous seizures have been observed in Pin1-knockout mice without any induction, suggesting that Pin1 may be a neuroprotective gene in the development of epilepsy, and its function may be associated with the regulation of excitatory and inhibitory synapses." (PMID 36304997, 2022). "Therefore, it is valuable to study the mechanism by which Pin1 acts on the PI3K/Akt pathway, and PI3K/Akt may be another potential target for epilepsy treatment." (PMID 36304997, 2022). "Therefore, we can hypothesize that the interaction between Pin1 and Notch1 pathway may play a role in epilepsy and that Notch1 may participate in epileptogenesis via the function of CaMKII and PKA." (PMID 36304997, 2022). "Pin1 also regulates Ca2+ influx by binding to salt-induced kinase 2 (SIK2) and decreasing the expression of p35, a negative regulator of Ca2+ influx, yet the effect is induced by high glucose, which is not the same as the microenvironment of epilepsy." (PMID 36304997, 2022).
Glucose intolerance (3 papers, 2015 to 2024). Glucose intolerance (GI) can be defined as dysglycemia that comprises both prediabetes and diabetes. "β-cell-specific Pin1 KO (βPin1 KO) mice developed glucose intolerance owing to reduced insulin secretion but preserved peripheral insulin sensitivity." (PMID 30096758, 2018). "Pin1 enhances insulin-induced IRS-1 tyrosine phosphorylation through its isomerase activity, and Pin1 knockout mice exhibit impaired insulin signaling with glucose intolerance." (PMID 26074875, 2015). "Similarly, Par14 enhances insulin-induced IRS-1 tyrosine phosphorylation, and Par14 knockdown exacerbated the glucose intolerance in Pin1 knockout mice." (PMID 26074875, 2015).
HCMV infection (3 papers, 2016 to 2021). "A general phenomenon of a virus-induced effect on the cellular level, observed already earlier, was confirmed here, namely a slight upregulation of lamin A/C pS22 and Pin1 as well as downregulation of lamin A/C by HCMV infection." (PMID 33499341, 2021). "Pin1 levels have been reported to increase with early kinetics during HCMV infection." (PMID 35062219, 2021). "Since Pin1 expression is activated by the transcription factor E2F, which is subject to the control of cell cycle progression, HHFs were synchronized at the G0 phase by serum starvation prior to HCMV infection." (PMID 27556400, 2016). "In the absence of Pin1, disruption of the nuclear lamina by pUL97 is decreased, suggesting that Pin1 participates in the modification of the nuclear lamina during HCMV infection." (PMID 35062219, 2021).
hyperparathyroidism (3 papers, 2013 to 2015). Hyperfunction of the parathyroid glands resulting in the overproduction of parathyroid hormone. "PIN1 was essential for KSRP mediated PTH mRNA decay such that mice lacking Pin1 expressed elevated serum PTH levels, mimicking hyperparathyroidism." (PMID 23675491, 2013).
hypophysis (3 papers, 2013 to 2016). "The first deviations from normal development are observed in pin1 mutants at the globular and heart stages of embryogenesis, when one to two thirds of pin1 embryos show disrupted hypophysis." (PMID 26821586, 2016).
acute kidney injury (2 papers, 2016 to 2021). Sudden and sustained deterioration of the kidney function characterized by decreased glomerular filtration rate, increased serum creatinine or oliguria. "The hypoxia/reoxygenation (H/R) model in human kidney (HK-2) cells and the I/R model in rats were assessed to investigate the role of Pin1 on I/R-induced acute kidney injury." (PMID 34373763, 2021). "Male Sprague-Dawley rats were used to establish the I/R model for 15, 30, and 45 min ischemia and then 24 h reperfusion, with or without the Pin1 inhibitor, to demonstrate the role of Pin1 in acute kidney injury." (PMID 34373763, 2021).
adenovirus infection (2 papers, 2019 to 2025). "First, adenovirus infection induced an EGFR stress response that generated a phosphorylated NFκB binding site for the peptidyl-prolyl isomerase Pin1, which is known to enhance NFκB activity by countering negative feedback control through ubiquitin (Ub)-mediated NFκB degradation." (PMID 31425554, 2019). "Additionally, we used adenovirus infection to overexpress Pin1 in astrocytes." (PMID 40385538, 2025).
age-related hearing loss (2 papers, 2021 to 2022). "However, the mechanism of PIN1 in age-related hearing loss (ARHL) remains unclear." (PMID 34285767, 2021). "PIN1 might regulate autophagy activity to induce the senescent of HEI-OC1cells and HCs, which will provide a theoretical support for the prevention and treatment of age-related hearing loss." (PMID 36340199, 2022).
allergic disease (2 papers, 2015 to 2018). An immune response that occurs following re-exposure to an innocuous antigen, and that requires the presence of existing antibodies against that antigen. "As seen in a variety of pathologies including cancer, allergy and infection, Pin1 dysregulation can have profound consequences." (PMID 25874604, 2015). "Subsequent studies also demonstrated an essential role for Pin1 in allergic disease." (PMID 25874604, 2015).
chronic kidney disease (2 papers, 2016 to 2024). Impairment of the renal function secondary to chronic kidney damage persisting for three or more months. "In summary, serum Pi driven by chronic renal disease or elevated by excess dietary Pi drives or initiates renal injury and triggers a Pin1 dependent, ECM remodeling process." (PMID 26914452, 2016). "However, the role of Pin1 in the chronic kidney diseases is unknown." (PMID 26914452, 2016).
colorectal tumor (2 papers, 2016 to 2022). "Even though overexpression of Pin1 is implicated in various tumors, little is known about its effect on CRC or colorectal tumor-initiating cells." (PMID 35433695, 2022). "The results suggest that targeting Pin1 in colorectal tumor-initiating cells is an appealing therapeutic approach to human CRC." (PMID 35433695, 2022). "However, although the present data suggest that targeting Pin1 in CD44+CD133+ colorectal tumor-initiating cells is a promising therapeutic approach, there are some limitations regarding the use of Pin1 inhibitors for treating human disease." (PMID 35433695, 2022). "Overall, these results indicate that chemical Pin1 inhibitors may be a valuable therapeutic option against colorectal tumor-initiating cancer cells." (PMID 35433695, 2022). "In addition, Pin1 overexpression might be attributable to stabilization of β-catenin and cyclin D1 in human colorectal tumor-initiating cells." (PMID 35433695, 2022). "Though the molecular mechanisms underlying Pin1 function in colorectal tumor-initiating cells require further study, it is not surprising that targeting Pin1 is considered a novel strategy to eliminate tumor-initiating cells and reduce the risk of cancer recurrence." (PMID 35433695, 2022). "Here, we showed that two chemical inhibitors of Pin1, Juglone and KPT6566, inhibit growth of colorectal tumor-initiating cells and colony formation." (PMID 35433695, 2022).
dyslipidemia (2 papers, 2016 to 2024). "These lines of evidence led us to consider the possibility of a close relationship between metabolic syndrome and increased Pin1 expression." (PMID 27618008, 2016). "We suspect that Pin1 alterations in some organs take part in the regulation of metabolic functions or even the onsets of metabolic syndromes, and we have thus been studying the roles of Pin1 in metabolic functions." (PMID 27618008, 2016). "In this review, we focus on the role of Pin1 in various metabolic disorders, including the components of metabolic syndrome." (PMID 27618008, 2016). "Pin1 associates with and controls key molecules (IRS-1, CRTC2, AMPK, eNOS, Runx2 and others) involved in metabolic functions or the development of metabolic syndromes." (PMID 27618008, 2016). "Indeed, we and other research groups have demonstrated that Pin1 contributes to glucose metabolism, the maintenance of vascular functions and bone formation, as it does to the development of metabolic syndromes." (PMID 27618008, 2016). "Although Pin1 expressions are well known to be markedly upregulated in different types of cancers, whether Pin1 protein levels are altered in metabolic syndromes remains unknown." (PMID 27618008, 2016). "These post-translational modifications of Pin1 are well known to correlate with cancer progression, but it is unclear whether these alterations contribute to the development of other diseases, such as metabolic syndromes." (PMID 27618008, 2016). "In addition, a Pin1 inhibitor or modulators of proteins upstream from Pin1 might be promising targets for treating metabolic syndromes including diabetic vascular dysfunctions." (PMID 27618008, 2016). "Thus, as with cancers, modifications of Pin1 may well contribute to the development of metabolic syndromes." (PMID 27618008, 2016). "Thus, the increased Pin1 expressions are considered to be causative for, rather than resulting from, various phenotypes among those associated with the metabolic syndrome." (PMID 27618008, 2016). "Finally, Pin1 expressions in serum might serve as disease markers because some investigators have indicated that altered Pin1 expressions are detectable in patients suffering from metabolic syndromes." (PMID 27618008, 2016). "In brain tissues, ApoE4 induces dyslipidemia leading to vascular dysfunction, reduced CBF, ischemia, hypoxia, inhibited autophagy, and may inactivate Pin1." (PMID 39857613, 2024).
embryonal carcinoma (2 papers, 2008 to 2023). A non-seminomatous malignant germ cell tumor characterized by the presence of large germ cells with abundant cytoplasm resembling epithelial cells, geographic necrosis, high mitotic activity, and pseudoglandular and pseudopapillary structures formation. "Western blotting was used to measure Pin1 expression in embryonal carcinoma cells (P19 cell lysates)." (PMID 38020885, 2023). "The purpose of the present study was to elucidate the effects of Pin1 and KPT6566 on TGCT carcinogenicity using P19 and NCCIT embryonal carcinoma cell lines." (PMID 38020885, 2023). "BNIP-H interacted with Pin1 after nerve growth factor-stimulation and they co-localized in the neurites and cytosol of differentiating pheochromocytoma PC12 cells and the embryonic carcinoma P19 cells." (PMID 18628984, 2008). "In the present study, we determined whether the small-molecule Pin1 inhibitor KPT6566 affected viability and tumorigenic potential of embryonal carcinoma cells." (PMID 38020885, 2023). "The embryonic carcinoma cell line P19 was also examined for the localization of BNIP-H and Pin1." (PMID 18628984, 2008).
infertile (2 papers, 2017 to 2023). "The effect of Pin1 dosage in Sertoli cells might be useful in the study of toxicant-mediated infertility, gonadal cancer, and for designing male contraceptives." (PMID 28765625, 2017).
male infertility (2 papers, 2019 to 2022). The inability of the male to effect fertilization of an ovum after a specified period of unprotected intercourse. "The effect of some of these polymorphisms or a combination of them would eventually imbalance the expression of PIN1, which has been associated with male infertility in animal models." (PMID 35743717, 2022). "Our experimental design allowed us to study the influence of the genetic variants located in the PIN1 locus on the susceptibility to male infertility and specially to identify their contribution to SCO as an etiologic factor." (PMID 35743717, 2022). "In this functional prioritization, we found further evidence that might support variants in PIN1 as genetic risk factors to suffer from spermatogonial depletion and to develop male infertility with a SCO." (PMID 35743717, 2022). "Our results emphasized the role of PIN1 as a risk locus for male infertility." (PMID 35743717, 2022). "There are also studies that point out that the lack of Peptidyl-prolyl cis/trans isomerase NIMA-interacting 1 (PIN1), which is essential for spermatogenesis, leads to male infertility, while FBXW7 is down-regulated when Pin1 is exhausted." (PMID 31779633, 2019).
metastatic disease (2 papers, 2012 to 2026). "Immunostaining results revealed elevated levels of SENP1, OCT4, CD133, N-cadherin, and PIN1 proteins in the HBx-shCtrl group, whereas these proteins were markedly reduced in both the liver and lung metastatic tumors in the SENP1-silenced groups." (PMID 41438340, 2026).
Myocardial fibrosis (2 papers, 2021 to 2024). "Contrary to other studies, a recent report illustrates that miR-34a ameliorates myocardial fibrosis by targeting Pin-1 signaling to suppress Col I production, viability, and migration in DCM." (PMID 39250437, 2024). "A novel reciprocal loop of TGF-β1/PML SUMOylation/Pin1 leading to myocardial fibrosis may exist." (PMID 34128158, 2021).
myocardial infarction (2 papers, 2021 to 2022). Gross necrosis of the myocardium, as a result of interruption of the blood supply to the area, as in coronary thrombosis. "GA can alleviate myocardial infarction-induced cardiac dysfunction and fibrosis through SUMOylation of the PML/Pin1/TGF-β1 pathway." (PMID 35707278, 2022). "Inhibition of SUMO-1 by ginkgoic acid alleviated myocardial infarction-induced heart dysfunction and fibrosis, and the SUMOylated PML/Pin1/TGF-β1 pathway is crucial for ginkgoic acid-inhibited cardiac fibrosis, wherein Pin1 functions as a positive regulator of TGF-β1 mRNA." (PMID 34128158, 2021).
neuropathy (2 papers, 2023). A disorder affecting the nervous system that manifests with pain, tingling, numbness, and/or muscle weakness. "In vertebrates, Pin1 knockout mice exhibit cyclin D1-null phenotypes and progressive age-dependent neuropathy, highlighting a pivotal role of Pin1 in cell proliferation and protecting against age-dependent neurodegeneration." (PMID 37791075, 2023).
non-small cell lung carcinoma (2 papers, 2015 to 2020). A group of at least three distinct histological types of lung cancer, including non-small cell squamous cell carcinoma, adenocarcinoma, and large cell carcinoma. "In cancer patients, a high expression of PIN1 correlates with a poor clinical outcome, lymph node metastasis in non-small cell lung cancer patients, and disease progression in patients with oral squamous carcinoma." (PMID 32258027, 2020). "Moreover, we observed endogenous Pin1–Rb co-localization by immunofluorescence in non-small-cell lung carcinoma H1299 cells, as well as binding in vivo by co-immunoprecipitation in H1299 and U2-OS cells." (PMID 25675300, 2015).
oral cancer (2 papers, 2024). "In this study, the potential effects of juglone, also known as PIN1 inhibitor, on oral cancer and carcinogenesis were investigated at the molecular level." (PMID 39202474, 2024). "Inhibits cell proliferation; apoptosis in OSCC cells, as evidenced by an increased percentage of cells in the sub-G1 phase of the cell cycle, annexin V-positive/propidium iodide-negative cells, and nuclear morphology; new chemotherapeutic agent targeting NF-κb and PIN1 in oral cancer." (PMID 39518052, 2024). "Therefore, it can be said that juglone, a strong PIN1 inhibitor, may be a potential candidate for treatment in oral cancer models." (PMID 39202474, 2024).